FOXO3 (forkhead box O3)
Diseases named in the same sentence as FOXO3 in open-access papers (continued):
Sharing a sentence is not in itself a finding about the gene and the disease.
neuroblastoma (continued). "The accumulation of ROS was essential for FOXO3-induced cell death in these cell types, since co-treatment with the ROS inhibitor N-Acetyl-L-cystein (NAC) rescued neuroblastoma cells from FOXO3-induced apoptosis." (PMID 23801966, 2013). "Knock-down of Bim rescues neuroblastoma cells from ROS-accumulation and FOXO3-induced apoptosis, whereas tetracycline-regulated Bim-expression alone is sufficient to induce ROS." (PMID 23801966, 2013). "In Microarray analyses, however, we identified the antioxidant enzyme SESN3 as a FOXO3 target in neuronal and neuroblastoma cells." (PMID 23801966, 2013). "The induction of Noxa by FOXO3 is also observed in neuroblastoma cells where it significantly contributes to mitochondrial cell death by releasing BAX and BAK from BclxL." (PMID 23828551, 2013). "In cultured neuroblastoma cells the activation of FOXO3 triggers the intrinsic death pathway and induces programmed cell death via induction of the pro-apoptotic BH3-only proteins Bim and Noxa." (PMID 23801966, 2013). "We demonstrated that FOXO3 induces apoptosis via Bim and Noxa in neuroblastoma cells, where PKB signaling is also frequently deregulated." (PMID 23828551, 2013). "FOXO3-triggered autophagy partially protects neuroblastoma cells from cell death." (PMID 28545464, 2017). "We therefore analyzed whether oxidative stress affects the expression of DEPP and thereby the induction of autophagy via FOXO3 in neuroblastoma cells." (PMID 28545464, 2017). "However, here we report for the first time that FOXO3 simultaneously modulates an autophagy program that partially protects neuroblastoma cells from undergoing apoptosis, suggesting a fragile balance between survival and death controlled by FOXO3." (PMID 28545464, 2017). "In neuroblastoma (NB), nuclear FOXO3 correlates with stage M disease and poor prognosis." (PMID 28869600, 2017). "Importantly, DEPP- and FOXO3 knockdown experiments revealed that the induction of the FOXO3/DEPP axis by cellular stress is essential to induce autophagy in neuroblastoma." (PMID 28545464, 2017). "• Etoposide- and doxorubicin-induced apoptosis of neuroblastoma cells was dependent on FoxO3-mediated Bim expression and ROS production that could be prevented by Bcl-xL." (PMID 26405162, 2015). "Phosphorylation of FOXO3 by PKB at distinct amino acids leads to its association with 14-3-3 proteins, resulting in export from the nucleus and as a consequence thereof loss of target gene regulation in neuroblastoma cells." (PMID 25261981, 2014). "FOXO3 activation has been shown to induce apoptosis in neuroblastoma cells." (PMID 25261981, 2014). "We recently provided evidence that the FOXO3-ATM complex also overcomes epigenetic silencing of the caspase-8 gene in human neuroblastoma cells by activating the ATM downstream target CREB which in turn triggers methylation-independent activation of the caspase-8 promoter." (PMID 23801966, 2013). "In addition FOXO3 represses the apoptosis-inhibitor protein Survivin and determines the sensitivity of neuroblastoma cells to DNA-damaging chemotherapeutic agents." (PMID 23801966, 2013). "Interestingly, the increase in the level of the decidual protein, C10ORF10/DEPP, induced by progesterone, a transcriptional target of Forkhead box O3 (FOXO3) that is present in mitochondria, mediates ROS accumulation and regulates FOXO3‐induced autophagy in human neuroblastoma cells." (PMID 40703196, 2025). "In neuroblastoma (NB), we recently demonstrated that nuclear FOXO3 promotes tumor angiogenesis in vivo and chemoresistance in vitro." (PMID 31591479, 2020). "Thus, the pro-survival role of FoxO3 in neuroblastoma appears to depend on target-gene regulation." (PMID 30646603, 2019). "As FOXO3 controls cellular ROS steady-state levels via DEPP expression, the present study was designed to investigate the impact of FOXO3 and DEPP on autophagy and associated effects on ROS-mediated cell death as well as therapy resistance in human neuroblastoma." (PMID 28545464, 2017).
neuroblastoma (continued). "As there is evidence for a protective role of autophagy against apoptosis contributing to chemotherapy resistance, we hypothesized that FOXO3 might, besides the regulation of apoptosis, also control a rescue pathway by inducing autophagy in neuroblastoma cells." (PMID 28545464, 2017). "In neuroblastoma cells an increased activity of the phosphatidylinositol-3 kinase (PI3K) protein kinase B (PKB/AKT) pathway was reported that contributes to therapy resistance and is associated with phosphorylation and functional inactivation of the transcription factor FOXO3." (PMID 25261981, 2014). "Although FOXO3 has been shown to induce a number of genes that protect against ROS suggesting that they play a critical role in keeping cellular ROS low, we recently demonstrated that in primary neurons and neuroblastoma cells FOXO3 may also increase mitochondrial ROS levels." (PMID 23801966, 2013). "In the neuroblastoma, the silencing of the lumican gene in FOXO3 expressing IMR32 and SK-N-SH neuroblastoma cells or adding a FOXO3 inhibitor that restricted lumican transcription resulted in these cells’ reduced migration capacity." (PMID 34572532, 2021). "The DEPP promoter, previously defined in a human neuroblastoma cell line as the −1116 bp sequence upstream of DEPP TSS, was shown to respond to FOXO3 transcription factors." (PMID 31963726, 2020). "FOXO3 triggers apoptosis via upregulation of the proapoptotic BH3-only proteins BIM and PMAIP1/NOXA in neuroblastoma cells." (PMID 28545464, 2017). "The FOXO3/DEPP-triggered autophagy pathway thereby partially protects against chemotherapy-induced cell death and attenuates apoptosis induction in neuroblastoma." (PMID 28545464, 2017). "To further prove that FOXO3 triggers autophagy via induction of ROS in neuroblastoma cells we performed immunoblot analysis on LC3 conversion in SH-EP/FOXO3 and NB15/FOXO3 cells treated with 4OHT and with NAC to scavenge ROS." (PMID 28545464, 2017). "In line, also MnTBAP efficiently abolished FOXO3-mediated LC3-II expression, indicating that FOXO3-mediated ROS accumulation triggers autophagy in neuroblastoma cells." (PMID 28545464, 2017). "After activation of FOXO3 by treatment with 100 nM 4OHT for 3 hours, DEPP expression was induced in the neuroblastoma cell lines SH-EP/FOXO3 and NB15/FOXO3 171 and 87 fold compared to untreated controls and in the leukemia cell line CEM/FOXO3 50 fold." (PMID 25261981, 2014). "Moreover, by inhibiting FOXO3 and weakening its binding with the LUM promoter, LUM expressions are suppressed, leading to reduced migration of neuroblastoma cells." (PMID 37692065, 2023). "Overexpression of FOXO3 and AKT inhibition increased apoptosis in neuroblastoma." (PMID 34831287, 2021). "As an additional important factor, forkhead-box-protein O3 (FOXO3) was found to be an important regulator of homeostasis that promotes tumor growth under hypoxic conditions and tumor angiogenesis in late-stage neuroblastoma." (PMID 35008547, 2021). "To determine whether LC3 and Gabarapl1 are also transcriptionally regulated by FOXO3 in neuroblastoma cells we measured the mRNA expression of LC3 and Gabarapl1 in SH-EP/FOXO3-shCtr and SH-EP/FOXO3-shDEPP-13 cells by quantitative RT-PCR analyses." (PMID 28545464, 2017). "This suggests that elevated DEPP expression does not constitute a death signal per se, but rather changes the ability of neuroblastoma cells to detoxify ROS and is therefore necessary, but not sufficient, for FOXO3-induced cell death." (PMID 25261981, 2014). "Notably, upon inhibiting FOXO3 by the small molecular weight compound repaglinide, the binding of FOXO3 to the LUM promoter was attenuated, abrogating the FOXO3-dependent lumican expression and decreasing neuroblastoma cell 2D- and 3D-migration." (PMID 34572532, 2021).
neuroblastoma (continued). "As the transcription factor FOXO3 is involved in the modulation of autophagy and DEPP is a transcriptional target of FOXO3, we wondered whether FOXO3 induces autophagy in neuroblastoma cells and whether this process is mediated via DEPP." (PMID 28545464, 2017). "However, SOD2 and Catalase were not regulated in neuroblastoma cells and therefore do not seem to contribute to the fluctuations of ROS levels during FOXO3-induced apoptosis." (PMID 23801966, 2013).
glioma (48 papers, 2011 to 2025). A benign or malignant brain and spinal cord tumor that arises from glial cells (astrocytes, oligodendrocytes, ependymal cells). "FOXO3 is a tumor suppressor whose activity is often suppressed in a variety of tumors, including gliomas." (PMID 39944825, 2025). "By activating AMPK, metformin promotes the nuclear translocation and transcriptional activity of FOXO3 and then inhibits the proliferation, self-renewal, and invasion ability of glioma stem cells." (PMID 39944825, 2025). "FOXO3 activation is sufficient to induce differentiation of glioma-initiating cells with stem cell-like characteristics and inhibit their tumor-initiating potential." (PMID 39944825, 2025). "Taken together, several conclusions can be obtained from these studies regarding the different aspects of FOXO3 in gliomas: (a) The expression and function of FOXO3 differ in glioma depending on the spatial localization of tumor cells and tumors grade." (PMID 37821870, 2023). "An important function of FOXO3 is its contribution to stem cell differentiation in both neural stem cells and glioma stem cells." (PMID 37821870, 2023). "Various upstream regulators of Akt such as CLK2 (oncogene), IGF1 (dual role), SPHK1(oncogene), CHAF1A (oncogene), and importantly FOXM1B (oncogene) was found to exert their function by affecting Akt/FOXO3 axis in gliomas." (PMID 37821870, 2023). "Drug screening identified metformin (MF), a biguanide and the most widely used drug for the treatment of type 2 diabetes, as an activator of FOXO3 in stem-like glioma-initiating cells." (PMID 36077758, 2022). "Previous studies have reported that circ-Foxo3 is involved in the development and tumorigenesis of a variety of cancers (bladder, gastric, acute lymphocytic leukemia, glioma, etc.)." (PMID 33833780, 2021). "The colony formation assay indicated that silencing PTEN, PHLPP2 or FOXO3 in miR-93 inhibitor transfected cells increased proliferation of glioma cells." (PMID 25823655, 2015). "In addition, FOXO3 was shown to act as a core component in the response of glioma cells to cellular stress, such as ROS production, hypoxia, glucose metabolism, and sirtuins." (PMID 37821870, 2023). "Also, in glioma stem cells FOXO3 is involved in radiotherapy resistance, as inhibition of FOXO3 enhances the response to radiotherapy." (PMID 31591479, 2020). "Herein, we found that miR-93 was significantly upregulated in gliomas, and overexpressing miR-93 activated PI3K/Akt signaling through downregulating PTEN, PHLPP2 and FOXO3 expression via targeting their 3′UTRs, subsequently resulting in glioma cell proliferation and progression." (PMID 25823655, 2015). "Thus, FOXO3 activators could be a potential molecular targeting drug for glioma-initiating cell-directed therapies." (PMID 36077758, 2022). "It has been shown that in gliomas OCT4 expression is maintained by the transcription factors FOXO1 and FOXO3 and suppressed by PI3K/Akt/mTOR, and its level is significantly enhanced when PI3K is inhibited simultaneously with mTOR or MEK." (PMID 38392188, 2024). "MF activates FOXO3 via AMP-activated protein kinase (AMPK) and thereby induces differentiation of stem-like glioma-initiating cells in vitro, and effectively suppresses their tumor formation in vivo." (PMID 36077758, 2022). "Recently, analysis of 297 glioma samples from the Chinese Glioma Genome Atlas for local immune signature genes identified AIMP1, FOXO3, and ZBTB16 as positive prognostic indicators well correlated with patient overall survival (OS)." (PMID 29379495, 2017). "Western blotting analysis showed that ectopic expression of miR-93 dramatically decreased, whereas inhibition of miR-93 increased, the protein expression of PTEN, PHLPP2 and FOXO3 in both LN18 and Hs683 glioma cells." (PMID 25823655, 2015). "To evaluate the effects of PTEN, PHLPP2 and FOXO3 on miR-93-induced glioma progression, we suppressed endogenous PTEN, PHLPP2 or FOXO3 expression with specific siRNAs." (PMID 25823655, 2015).
glioma (continued). "Metformin activates FOXO3 and promotes the differentiation of these stem cell-like glioma-initiating cells into non-tumorigenic cells." (PMID 39944825, 2025). "At the same time, metformin may also down-regulate the expression of FOXO3 and AKT, and further inhibit the proliferation and invasion ability of glioma stem cells." (PMID 39944825, 2025). "There are several upregulated ncRNAs in glioma, including miR-10b, miR-27a, miR-93, miR-155, miR-184, Circ-DONSON, and Inc-TALC that their oncogenic activity was shown to be exerted through repressing FOXO3." (PMID 37821870, 2023). "We also identified forkhead box O3 (FOXO3) as an integrator of the MAPK and PI3K pathways in the maintenance of stem-like glioma-initiating cells, and FOXO3 activation is sufficient to induce differentiation and suppress the tumor-initiating potential of stem-like glioma-initiating cells." (PMID 36077758, 2022). "FoxO3 transcriptional activity attenuates ROS levels, reducing HIF-1α stabilization in normal cells, however as FoxO3 activity is often downregulated due to oncogenic signaling, HIF-1 is further stabilized by increased ROS tolerance in glioma." (PMID 28491867, 2017). "Substrates affected include FOXO transcription factors (FOXO3 and FOXO4) and BCL-2 protein family (BAD, BCL2, and BCL2L1) in which the phosphorylated state may ensure glioma cell survival under stressful environments." (PMID 21955618, 2011). "In addition, Met can activate FOXO3 to promote the differentiation of stem-like glioma-initiating cells into nontumorigenic cells." (PMID 34546972, 2021). "Additionally, metformin may target tumor-initiating stem cell-like glioma cells, also called Glioma Stem Cells (GSC), through AMPK-dependent inhibition of FOXO3 and AKT." (PMID 25867026, 2015). "MiR‐93 in glioma cell lines and glioma tissues was significantly upregulated, and it is correlated with clinicopathologic grading and survival in patients and may directly activate PI3K/Akt signaling by suppressing PTEN, PHLPP2, and FOXO3 expression targeting 3′‐untranslated regions (UTRs)." (PMID 36281584, 2023). "Metformin activation of the FOXO3-AMPK pathway that eliminates cells, which initiate gliomas by inducing differentiation into nontumor cells, has been described in the brain." (PMID 28634570, 2017). "As an alternative mechanism to genetic alteration, overexpression of miR-93 might explain the observed over-activation of PI3K/Akt in glioma cells lack of PI3K amplification and genetic losses of PTEN, PHLPP2 and FOXO3." (PMID 25823655, 2015).
cardiac hypertrophy (46 papers, 2010 to 2026). "Our findings show that upregulation of miR-182 is associated with angiogenesis-induced myocardial hypertrophy and decreases the expression of branched chain aminotransferase 2 (Bcat2), forkhead box O3 (Foxo3), and adenylate cyclase type 6 (Adcy6)." (PMID 26888314, 2016). "It has been previously demonstrated that FoxO3 activates the expression of catalase in response to oxidative stress, thereby inhibiting cardiac hypertrophy." (PMID 40785055, 2025). "Relevant studies confirm that Sirt6 activation enhances autophagic flux by preventing the accumulation of autophagy‐related factors and ameliorates cardiac hypertrophy via inhibition of the Akt/FoxO3 pathway, which promotes autophagy." (PMID 41466491, 2025). "For example, heart-related circRNA (HRCR) inhibits cardiac hypertrophy and heart failure by adsorbing miR-233, while circ-Foxo3 facilitates cardiac aging and circ-ANRIL is concerned with atherosclerosis." (PMID 36835653, 2023). "miRNA-212 was found to regulate the process of cardiac hypertrophy by directly regulating Forkhead box O3 (Foxo3)." (PMID 34977165, 2021). "Previous studies indicated that SIRT3-mediated deacetylation of FOXO3 decreased cellular ROS levels and ameliorated cardiac hypertrophy in mice." (PMID 33298860, 2020). "An increased phospho-FOXO3/total FOXO3 ratio is considered to be a characteristic shift in pressure-overload-induced cardiac hypertrophy forms." (PMID 31380269, 2019). "These miRNAs affect cardiac hypertrophy by targeting the anti‐hypertrophic and proautophagic transcription factor forkhead box O3 (FoxO3), leading to induction of the prohypertrophic calcineurin/NFAT signalling pathway." (PMID 29972883, 2018). "FoxO3 induces Atrogin-1 and MuRF1 transcription, and counteracts cardiac hypertrophy in multiple pathological settings." (PMID 27349908, 2016). "And FoxO1 and/or FoxO3 are/is considered as apoptosis-regulating gene for the onset of diabetic cardiomyopathy, cardiac hypertrophy and ischemic heart disease." (PMID 24489705, 2014). "It has been reported that the upregulation of FoxO1 and FoxO3 appears to disrupt cardiac hypertrophy." (PMID 24489705, 2014). "Inhibition of FOXO3 was related to cardiac hypertrophy and heart failure in mice." (PMID 37985893, 2023). "Then, FOXO1 and FOXO3 induced autophagy and reduced cardiac hypertrophy after IRI5." (PMID 37985893, 2023). "Additionally, the positive regulation of autophagy by SIRT6 prevents isoproterenol-induced myocardial hypertrophy, possibly by attenuating Akt signaling and promoting accumulation of the FOXO3 transcription factor in the nucleus." (PMID 37754811, 2023). "Our results are following most of the phenotypes observed in antimiR-132 treated TAC animals as well miR132/212 KO mice, in which these two miRs regulated cardiac hypertrophy and autophage by directly targeting FoxO3 and more resistant to pressure overload induced heart failure." (PMID 33816571, 2021). "However, both the HW/BW ratio and heart size were further elevated in CKO mice compared with CON mice exposed to PQ, suggesting that FoxO3 is necessary to protect against the cardiac hypertrophy induced by oxidative stress." (PMID 31264342, 2019). "In addition, both FoxO1 and FoxO3 negatively regulate cardiac hypertrophy." (PMID 23308102, 2013). "Activation of FoxO1 and FoxO3a plays a main role in cardiac hypertrophy but unlike FoxO1, FoxO3 levels are notably reduced in uremic hearts." (PMID 36982497, 2023). "Although, the increased phospho-FOXO3/total FOXO3 ratio is a characteristic shift in cardiac hypertrophy forms; it seems to be independent of the effect of miR-212 in chronic RIHD." (PMID 31380269, 2019). "Mice lacking FoxO1 are embryonically lethal by E10.5 due to impaired vasculogenesis, and mice lacking FoxO3 are viable but develop cardiac hypertrophy as adults, indicating the different functions of FoxO1 and FoxO3 in the cardiovascular system." (PMID 31264342, 2019).
cardiac hypertrophy (continued). "miRNA-212/132 family induce both cardiac hypertrophy and heart failure by activating pro-hypertrophic calcineurin/NFAT signaling, while inhibiting autophagic response upon starvation by directly targeting the anti-hypertrophic and pro-autophagic FoxO3 transcription factor." (PMID 31100777, 2019). "Thus, we do not exclude the role of FoxO3, another major isoform of the FoxO family expressed in the heart, in mediating autophagy and consequently mediating regression of cardiac hypertrophy by DeTAC or destretch." (PMID 23308102, 2013). "However, downregulation of FoxO1 significantly attenuated DeTAC- and de-stretch-induced regression of cardiac hypertrophy, suggesting that FoxO1 may have non-overlapping functions compared to FoxO3 that induce regression of cardiac hypertrophy." (PMID 23308102, 2013).